RNU6-1248P (RNA, U6 small nuclear 1248, pseudogene)
Gene: Small nuclear RNA gene on chromosome 1 (223,690,051 to 223,690,114, forward strand). Ensembl gene ENSG00000212398.
Homologues: Orthologues: guinea pig U6 (92% identical), dog U6 (83% identical). Paralogues in human: RNU6-1050P (97% identical), RNU6-1060P (97% identical), RNU6-116P (97% identical), RNU6-1243P (97% identical), RNU6-24P (97% identical), RNU6-748P (97% identical), RNU6-829P (97% identical), RNU6-949P (97% identical), RNU6-1024P (95% identical), RNU6-1266P (95% identical), RNU6-15P (95% identical), RNU6-19P (95% identical), and 1285 more.